CXCR2 (C-X-C motif chemokine receptor 2)
Diseases named in the same sentence as CXCR2 in open-access papers (continued):
Sharing a sentence is not in itself a finding about the gene and the disease.
cancer (continued). "Both the HFD and the cancer cells increased the expression of most genes; however, especially Il1b, Ym1, Cxcl2, Cxcl3, and Cxcr2 were among the most responsive genes to both the HFD and the cancer cells in the PSF which were further exacerbated by the combination of the HFD and cancer cells." (PMID 38264656, 2023). "However, it should be considered that CXCR2 expression is not exclusive to neutrophils, but it is also expressed by other cells, including some cancer cells." (PMID 35954190, 2022). "Targeting CXCR2 in cancer management is a promising adventure but might just not be totally efficient or curative due to the complexity of the development and metabolic outlook of cancer." (PMID 36164329, 2022). "CXCR2 stained immune granulocytic cells and not cancer cells." (PMID 34066060, 2021). "CXCL1/CXCR2-mediating signaling cascades, such as PI3K/Akt, mitogen-activated protein kinase (MAPK), and nuclear factor kappa-light-chain-enhancer of activated B cells (NF-κB), have been considered the regulatory signaling pathways for migration and invasion in several cancer cells." (PMID 34760697, 2021). "If blocking CXCL5’s receptor CXCR2 is detrimental to the proliferative state of the cancer cells in dead bone cultures, then blocking CXCR2 with the selective non-peptide CXCR2 antagonist SB225002 (antCXCR2) should attenuate CXCL5 activity by inhibiting CXCR2 and reduce cancer cell proliferation." (PMID 31562303, 2019). "Although the conventional treatment of cancer might affect the expression of CXCR2, the analysis of conventional treatment were not conducted, which might affect the appliance of the results in this study." (PMID 29599927, 2018). "The rest 45 articles were retrieved for full-text review, from which 33 were excluded: 25 not focusing on the expression of CXCR2 in cancer patients and 8 without efficient data on the expression of CXCR2 or overall survival (OS) or recurrence-free survival (RFS) to calculate HR." (PMID 29599927, 2018). "It is interesting to show that the expression of IGFBP1 and IL8, a chemokine activated by CXCR2, were also up-regulated in this present study, thus it is speculated that the BLE may have an anticancer property that may involve the mediation of cancer cells senescence." (PMID 27635343, 2016). "This study confirms that mRNA for CXCR2, VEGF-A, MMP11 and TGF-β mRNA's are all significantly increased after exposure to volatile anaesthetics, indicating the activation of key molecular mediators of metastasis such as cancer cell transformation, basement membrane degradation and angiogenesis." (PMID 27028996, 2016). "Furthermore, because an NF-κB inhibitor attenuated CXCL1-induced cell invasion in CXCR2 positive cells, our results suggest that the CXCL1-CXCR2 axis may accelerate cancer progression by potentiating NF-κB signaling." (PMID 24376747, 2013). "In addition to the lack of a homologous genetic model, efforts to determine the function of CXCL8 in cancer progression are complicated by redundancy of the chemokines that share CXCR1 and CXCR2, and by the expression of cytokines other than CXCL8 in response to an upstream stimulus." (PMID 24224100, 2013). "Furthermore, the CXCL1/CXCR2 axis can induce PMN-myeloid-derived suppressor cells (MDSCs) accumulation in the TME and induce CD8+ T cell exhaustion, which may offer a potential therapeutic strategy for cancer therapy." (PMID 38515019, 2024). "Interestingly, CXCR2 activation may not increase or may even inhibit proliferation in certain types of cancer." (PMID 37686093, 2023). "Since expression of CXCR2 and CXCR4 is not restricted to neutrophils, we sought to directly explore the aging process of circulating neutrophils in animal models of cancer." (PMID 34876407, 2021). "Inhibition of some SASP elements, such as IL-6, C-X-C motif chemokine receptor 2 (CXCR2), IGFBP7 prevents senescence, and the lack of senescence may promote cancer development." (PMID 36232388, 2022).
cancer (continued). "AZD5069 recognised by CXCR2 could improve the lack of the tumour suppressor phosatase and tensin homolog(PTEN), which can inhibit cancer cell survival through the inactivation of aldose reductase(AR), hypoxia induced factor‐1(HIF‐1) and nuclear factor‐kappa B(NF‐κB) transcription factors." (PMID 38450975, 2024).
infection (162 papers, 2007 to 2025). The state of being infected such as from the introduction of a foreign agent such as serum, vaccine, antigenic substance or organism. "Our findings provide evidence that oral administration of a CXCR4 antagonist can effectively correct blood and BM neutrophil abnormalities and reduce infection susceptibility in a CXCR2 LOF mouse model." (PMID 41451234, 2025). "We further demonstrated that with regulated CXCL2 chemokine expression levels, IL-27Ra-deficient neonatal mice had more CXCR2+ mononuclear cells present at the site of infection." (PMID 40977737, 2025). "CXCR2 and its associated ligands are one of the major recruiters of neutrophils to sites of infection and injury." (PMID 41228334, 2025). "This study investigated the effects of chronic oral administration of a CXCR4 antagonist on neutrophil abnormalities and infection susceptibility in a CXCR2 LOF mouse model." (PMID 41451234, 2025). "Given the key role of CXCR2 as a mediator of neutrophil recruitment and activation, we thus investigated the effects of either stimulating murine Cxcr2 expression or antagonizing CXCR2 signalling during S. aureus implant-associated infection." (PMID 38567642, 2024). "In septic mice, fewer Mincle-deficient neutrophils infiltrated into the infection site due to reduced surface expression of CXCR2 and increased G protein–coupled receptor kinase 2 (GRK2) expression." (PMID 28112221, 2017). "The results showed that Cxcr2 deficiency resulted in higher susceptibility to the infection and, interestingly, it fully overcame both Gbp4- and Asc- induced infection resistance and caspase-1 activity." (PMID 27363812, 2016). "As CXCR2 is crucial for neutrophil influx in response to polymicrobial infection, decreased expression of this receptor is associated with decreased neutrophil influx, increased bacterial growth and greater lethality." (PMID 26147469, 2015). "To confirm the deleterious role of neutrophils during B. thailandensis infection, we performed parallel studies in mice deficient in expression of CXCR2, the chemokine receptor most critical for neutrophil recruitment to infection sites." (PMID 25166912, 2014). "In this study, we investigated the impact of a CXCR4 antagonist on the pathogenic phenotypes seen in patients with chronic neutropenia, including abnormalities in blood and BM neutrophil levels, as well as infection susceptibility, in a pharmacologically induced CXCR2 LOF mouse model." (PMID 41451234, 2025). "Moreover, previous studies have indicated that the increased susceptibility to infection observed in Cxcr2-/- and Cxcl1-/- mice is linked to impaired neutrophil recruitment into infected tissues." (PMID 41451234, 2025). "Thus, we assessed CXCR2 status in the lungs of beta variant-infected mice over the course of infection." (PMID 36005818, 2022). "In an intraperitoneal infection model, depletion of neutrophils within the first four days of infection resulted in mortality associated with severe lesions and increased systemic parasite burdens, and a similar result was seen with CXCR2 knockout mice that are defective in neutrophil recruitment." (PMID 33505924, 2020). "Furthermore, Cxcr2 expression in tissues associated with sterile implants was unchanged in mice receiving any dose of Lcn2, revealing that recruitment of CXCR2-expressing cells was dependent on infection." (PMID 38567642, 2024). "However the similar wound healing phenotype in antibody and FcRg deficient mice suggests that timely, CXCR2-driven lesion contraction during challenge infection may require the concerted activation of MΦ and MF by both antibodies and helminth products." (PMID 25806513, 2015). "Hematopoietic CXCR2 is key for innate immunity in infection, as its depletion can lead to massive bacterial overgrowth with fatal for the host consequences." (PMID 40413164, 2025).
infection (continued). "The results also showed that the infection to HTLV‐1 significantly increased CXCR2 expression in the aortic tissue compared to the control group (p < 0.05)." (PMID 40495291, 2025). "The results uncovered that during infection WT neonatal mice fail to increase expression of CXCR2 but upregulate the cognate ligand CXCL2 significantly." (PMID 40977737, 2025). "We observed an approximate two-fold increase in CXCR2 expression in splenic neutrophils from WT pups during infection relative to uninfected controls." (PMID 40977737, 2025). "The infection-induced activation of cell motility was dependent on both CXCR2 and CCR2, and IL-8 stimulated filopodia-mediated cell motility." (PMID 40353220, 2025). "CXCR2 is also crucial for the rapid migration of neutrophils to sites of infection or inflammation, ensuring an effective immune response." (PMID 41451234, 2025). "When mice were monitored up to 14 days post-infection, CXCR2 LOF mice also exhibited significantly reduced overall survival compared to control mice, and this reduction appeared to improve with CXCR4 antagonist treatment." (PMID 41451234, 2025). "Here we further explored the mechanistic insights of the CXCR2/CXCL2 signaling axis limiting the infection in WT and IL-27Rα KO neonatal mice using an n vivo model and ex vivo studies with primary cells." (PMID 40977737, 2025). "Conversely, IL-27Rα KO neonates increase CXCR2 expression significantly in the spleen during infection but fail to upregulate CXCL2 transcripts." (PMID 40977737, 2025). "Several pieces of prior evidence point to the importance of CXCR2 in S. aureus planktonic infections." (PMID 38567642, 2024). "For CD62L, positive cells exhibited lower levels of molecule surface expression during the infection, while expression levels remained unchanged for CXCR2+ cells." (PMID 39156897, 2024). "In S. suis-infected mice, blood neutrophils show an increased expression of CD11b, the shedding of the L-selectin CD62L and less cells were positive for CXCR2 expression, suggesting an activated phenotype for the neutrophils during the infection." (PMID 39156897, 2024). "This has been observed using other CXCR2 antagonists in disparate disease models, and reveals a possible immune adaptive mechanism to increase neutrophil chemotaxis to the site of infection." (PMID 38567642, 2024). "We observed a twofold increase in Cxcr2 transcription in implant-associated tissues from infected compared to sterile mice, indicating an increased presence of CXCR2-expressing cells at active infection sites." (PMID 38567642, 2024). "The RNA-sequencing data also showed increased expression of the marker gene Cxcr2 suggesting increased recruitment of myeloid cells at week 4 post-infection in the vapC12 mutant infected mice." (PMID 38515752, 2024). "The CXCLs/CXCR2 axis mediates the arrival of neutrophils at inflammatory sites, and plays an important role in anti-infection and control of pathogen invasion." (PMID 38351296, 2024). "Following extravasation to the site of infection, neutrophils downregulate CXCR2 and upregulate CCR1, 2, and 5, which cumulatively boosts neutrophil ROS production and phagocytic activity." (PMID 39193987, 2024). "CXCR2 has also been identified as a cellular target for S. aureus ɣ-hemolysin AB, leukotoxin ED and Staphopain A15, highlighting the important role CXCR2 likely plays during infection." (PMID 38567642, 2024). "During parasite challenge in PHCF, CXCR2 expression was significantly downregulated at 1 h but recovered at 6 h post infection." (PMID 36936778, 2023). "Antibody blockade of chemokine receptor 2 (CXCR2) and infection of CXCR2 knockout mice substantially reduces propagation owing to loss of recruitment of ancillary uninfected neutrophils." (PMID 37228668, 2023). "CXCR2, a chemokine receptor, is expressed on activated neutrophils to enable migration towards sites of inflammation or infection." (PMID 37686072, 2023).
infection (continued). "CXCL8-CXCR1/CXCR2 interaction is one of the main regulators during infection by exerting neutrophil chemotaxis and activation." (PMID 36725964, 2023). "Chemokine (C-X-C motif) receptor 2 (CXCR2) is a critical chemokine receptor responsible for neutrophil chemotaxis to infection sites." (PMID 37533081, 2023). "Typical inflammatory chemokines, including Ccl4, Ccl3, Cxcl2, Cxcl3, and Cxcr2, induces immune cells to enter the site of infection during the immune response." (PMID 37580334, 2023). "CXCL5, known as LIX (LPS-induced CXC chemokine in mice), can activate neutrophils and attract them into tissues during inflammation and infection via its receptor, CXCR2." (PMID 35743888, 2022). "Spn infection of CXCR2 knockout mice or mice given a CXCR2 antagonist resulted in a defect in neutrophil influx and an associated increase in bacterial counts in BALF and lungs." (PMID 35646729, 2022). "NETs are extracellular scaffolds generated from neutrophils after CXCR2 activation during infection." (PMID 36451225, 2022). "The genes encoding the chemokine receptors CXCR1 and CXCR2 were also upregulated in the HC fed cows; these are both important in stimulating chemotaxis of PMN toward sites of infection as well as activating biochemical processes that kill invading bacteria." (PMID 36613482, 2022). "The possible protective role of tBHQ during infection is also suggested by the upregulation of Cxcr2." (PMID 35629310, 2022). "Neutrophils are critical in the acute inflammatory response to infection, and the complete ablation of neutrophils will lead to increased risks of infection, as with the antagonism of CXCR2 in COPD and delayed healing." (PMID 35039631, 2022). "Inflammation and infection enhance CXCR2 expression on cells, especially neutrophils, where it activates pathogen clearance." (PMID 36451225, 2022). "In the course of infection, inflammation also enhances CXCR2 expression on hepatocytes and cholangiocytes, resulting in their proliferation and angiogenesis, which are vital for liver regeneration." (PMID 36451225, 2022). "As there were 7 out of 10 pathways was related to infection or lymphocyte immunity, such as IL-6, IL-8, CXCR2, TGF-β, autophagy, and HIV-1 replication, whereas BMP singling was associated with extracellular interactions." (PMID 35401158, 2021). "The GSDMD−/− mice were treated i.p. with SB225002 (Cxcr2 inhibitor) or vehicle 1 h prior to infection and 23 h post-infection." (PMID 34011393, 2021). "CXCR2-mediated neutrophils play an important role in anti-infection and control pathogen invasion.Current evidence suggests that TICs in the TME serve as promising therapeutic targets." (PMID 34025668, 2021). "Downregulation of the CXCL1/2/5-CXCR2 axis, as demonstrated in the CXCL5-/- infection mouse model and the CXCR2 blockade model, enhanced CXCL13 expression in infected lungs as soon as during the innate immunity stage." (PMID 34868067, 2021). "Control mice treated with PBS had 23.8 ± 8.0% of neutrophils expressing CXCR2 in their blood, which rapidly increased to 55.8 ± 2.2% by three hours (p < 0.0001), and then remained steady up to 24-h post-infection." (PMID 32882969, 2020). "In this study, we investigated the effects of bystander infections on the physiologic role of the chemokine receptor Cxcr2 using Cxcr2-null mice." (PMID 32041848, 2020). "At later stages, when the infection is well-established, neutrophils are recruited primarily through Cxcr2 and Cxcl8a secreted by macrophages and epithelial cells." (PMID 32161595, 2020). "Interaction between CXCL2 and CXCR2 plays an important role in the recruitment of neutrophils into infection sites." (PMID 32984356, 2020). "Modulating neutrophil activity at the infection site with two different methods, Tg(mpx:rac2D57N) and chemical inhibition of Cxcr2, resulted in increased larval host death." (PMID 31932292, 2020).
infection (continued). "Compared to patients with infection, CXCR2 surface level decreases at the onset of the disease in septic shock patients." (PMID 33424860, 2020). "By contrast, in conditions of bystander infections, Cxcr2 null mice exhibit an impaired reproductive ability and reduced development of reproductive organs." (PMID 32041848, 2020). "Rats were treated with the CXCR2 antagonist at the time of infection (0 dpi) or at 3 dpi prior to neutrophil infiltration into the brain." (PMID 31220182, 2019). "For example, CXCR2, a key chemokine receptor that is a member of the G protein-coupled receptors superfamily, is essential for inflammatory cells migration to infection sites." (PMID 31417691, 2019). "Upon infection, percentage of circulating granulocytes and expression of CXCR2 on granulocytes were significantly reduced by Tacrolimus." (PMID 30643171, 2019). "As previously illustrated, CXCR2 knockout mice were more susceptible to HSK than WT mice, which supports the relevance of neutrophils in the early stages of infection." (PMID 30998796, 2019). "Stimulating the CXCR2 signaling axis during infection increased viral burden in primary dissemination organs (i.e., spleen and lungs) and resulted in increased SG seeding." (PMID 31239384, 2019). "CXCR2 was the most predominant CR observed in both circulating and lung-infiltrated neutrophils after infection." (PMID 31041196, 2019). "Upon pulmonary infiltration in response to infection, these neutrophils exhibited decline in CXCR2-positive staining, but remained highly induced at over 60% positivity compared to other induced CRs in infected-lungs." (PMID 31041196, 2019). "CXCR2 also represents a viable target for promoting remyelination following traumatic injury, dysmyelinating conditions, or infection." (PMID 30648122, 2018). "CXCL5 is a chemoattractant responsible for mediating neutrophil recruitment during inflammation and infection and binds to CXCR2, which is present especially on the surface of immune cells, e.g. PMN49,50." (PMID 29615632, 2018). "Specifically, Mincle appears to be necessary for neutrophil infiltration into the site of infection, in part, through upregulating CXCR2-mediated F-actin polymerization and chemotaxis." (PMID 28112221, 2017). "Neutrophils from antibiotic pre-treated mice had diminished surface expression of the chemokine receptor CXCR2, potentially explaining their inability to migrate to the site of infection." (PMID 28817707, 2017). "Our study implicates Mincle as a promoter of neutrophil recruitment into foci of infection by enhancing CXCR2 signaling." (PMID 28112221, 2017). "The recruitment of neutrophils into infection sites is mainly mediated by CXCR2 functioning with CXCL1 and CXCL2." (PMID 28878779, 2017). "The levels of IFNγ,IL-12/IL-23 p40, IL-1β, CXCL1/KC as well as the expression of CXCR2 wereincreased in the lung of M-TNFR1 KO as compared with TNFR1 KO 3 weekspost-infection, and further increased in both groups at 4–5 weeks." (PMID 26931771, 2016). "The CXCR2, alternatively known as IL-8RB, is critical for the recruitment of neutrophils from the circulation to the site of infection." (PMID 26402907, 2015). "Blockade of CXCR2 during Hpb challenge infection reproduced the delayed wound repair observed in helminth infected Aid-/- and Fcrg-/- mice." (PMID 25806513, 2015). "Recently, CXCR2 was reported to be the functional receptor for CXCL8_L1 in zebrafish where it is known to be involved in neutrophil recruitment during local infections, even though both CXCR1 and CXCR2 are expressed in neutrophils." (PMID 24613851, 2014). "CXCR2 down-regulation leads to insufficient neutrophil recruitment to the site of infection, impaired bacterial containment, uncontrolled systemic inflammation and a poor prognosis." (PMID 24357647, 2014).